TNF (tumor necrosis factor)
Diseases named in the same sentence as TNF in open-access papers (continued):
Sharing a sentence is not in itself a finding about the gene and the disease.
viral myocarditis (continued). "It was found that the expression levels of various genes involved in PGC-1α, fatty acid β-oxidation, and oxidative phosphorylation signaling pathways decreased in viral myocarditis, and these levels were significantly negatively correlated with the expression of pro-inflammatory cytokines (TNF-α)." (PMID 41585875, 2025). "TNF and nitric oxide (NO) play an important role in the pathogenesis of viral myocarditis." (PMID 35163412, 2022). "Andrographolide may improve viral myocarditis by inhibiting the increase in serum TNF-α, hs-CRP and cTnI levels caused by viral myocarditis, activating the IL-10/STAT3 anti-inflammatory pathway, and inhibiting the PI3K/AKT/NF-κB pathway." (PMID 36238575, 2022). "As indicated in the analysis, these DEGs were enriched in ‘TNF signaling pathway’, ‘Cytokine-cytokine receptor interaction’, ‘IL-17 signaling pathway’, and ‘NF-kappa B signaling pathway’, whose roles were also vital in other viral myocarditis." (PMID 35037831, 2022). "TNF-α treatment played a protective role in the acute stage of viral myocarditis in mice." (PMID 35204082, 2022). "They found that α7 nAChR activation increases STAT3 phosphorylation, decreases TNF-α and IL-6 expressions, and ultimately reduces viral myocarditis, indicating that α7 nAChR agonists could be a promising new strategy for patients with viral myocarditis." (PMID 33425684, 2021). "Serum TNF-α and mRNA expression in patients with viral myocarditis increase." (PMID 33817135, 2019). "Therefore, a prospective clinical study using larger sample sizes or high quality meta-analysis were needed to further evaluate the diagnostic performance of serum CK-MB, TNF-α and hs-CRP in children with viral myocarditis." (PMID 33817135, 2019). "Finally, nicotine treatment reduced inflammatory cytokines (IL-1β, IL-6, and TNF-α) in the myocardium, ameliorated the necrosis of cardiomyocytes and cellular infiltration in mice with viral myocarditis." (PMID 30176160, 2018). "Moreover, the inhibition of α7nAchR reduces the phosphorylation of STAT3, increases the levels of TNF-α and IL-6, and, ultimately, aggravates viral myocarditis." (PMID 25396421, 2014). "Additionally, the administration of Ad-IL-17AR:Fc consistently reduced the systemic TNF-α and IL-6 production in the supernatants of the heart homogenates on day 90 post-infection in viral myocarditis." (PMID 23977238, 2013). "While Th1 and Th17 cells release cytokines such as IL-17, IL-21, TNF, and IFN-γ, thereby exacerbating the progression of viral myocarditis, Th2 and Treg cells exhibit a protective effect against the disease." (PMID 40234407, 2025). "In the acute phase of viral myocarditis, CVB3 internalization leads to increased secretion of IL-6, IL-1β, TNF-α, and IL-8/C-X-C motif chemokine ligand 8, and infected neutrophils released MPO and triggered NETosis in the presence of TNF-α." (PMID 33680285, 2021). "Among them, tumor necrosis factor (TNF)-α, interleukin (IL)-1, and IL-6 are the three representative proinflammatory cytokines of human and animal viral myocarditis." (PMID 28197102, 2017). "We also inferred that in mice with viral myocarditis, methyllycaconitine blocked α7nAchR, decreasing the phosphorylation of STAT3; this resulted in the up-regulation of the expression of the cytokines TNF-α and IL-6 and aggravated the inflammatory response." (PMID 25396421, 2014). "In acute viral myocarditis, activation of α7nAchR increases the phosphorylation of STAT3, reduces the levels of TNF-α and IL-6, and, ultimately, alleviates viral myocarditis." (PMID 25396421, 2014). "In this study, we showed increased expression levels of proinflammatory cytokines (TNF-α, IL-6, and MCP-1) as well as antiviral cytokines (IFN-β and IFN-γ) and an anti-inflammatory cytokine (IL-10) due to viral myocarditis in cardiac tissue." (PMID 25374444, 2014).
viral myocarditis (continued). "Thus, we inferred that in mice with viral myocarditis, nicotine activated α7nAchR, increasing the phosphorylation STAT3; this resulted in the down-regulation of the expression of the cytokines TNF-α and IL-6 and relieved the inflammatory response." (PMID 25396421, 2014). "From this, we speculated that the cholinergic anti-inflammatory pathway did not affect the production and release of IFN-γ in viral myocarditis, the reduction in the inflammatory response was through the down-regulation of IL-1β, IL-6, and TNF-α, not IFN-γ." (PMID 28197102, 2017).
amoebiasis (40 papers, 2011 to 2025). "For example, lncRNA BX470102.1 is involved in amoebiasis, Kaposi sarcoma-associated herpesvirus infection, TNF signaling pathway, and IL-17 signaling pathway by targeting multiple target genes such as IL-6, CXCL2, and PTGS2." (PMID 36457749, 2022). "Activated monocytes/macrophages produce TNF-α, which induces parasite motility that is essential for pathogenic amebiasis." (PMID 22140588, 2011). "KEGG pathway analysis indicated that the up-regulated DEGs were significantly enriched in Complement and coagulation cascades, Amoebiasis and TNF signaling pathway." (PMID 35719390, 2022). "The analysis of KEGG pathway indicates that the DEGs were significantly enriched in Complement and coagulation cascades, Amoebiasis, TNF signaling pathway, bile secretion, and Mineral absorption." (PMID 35719390, 2022). "KEGG pathway analysis indicated that the up-regulated genes were significantly enriched in Complement and coagulation cascades, Amoebiasis and TNF signaling pathway, while the down-regulated genes were mainly enriched in bile secretion and Mineral absorption." (PMID 35719390, 2022). "KEGG pathway analysis showed the primary up-regulated pathway to be in cancer, followed by metabolic pathways, PI3K-Akt signaling, focal adhesion, amoebiasis, cytokine-cytokine receptor interaction, and TNF signaling." (PMID 36262185, 2022). "The most enriched pathways of down-regulated DEMs were connected with the TNF signaling pathway, cytokine−cytokine receptor interaction, and amoebiasis." (PMID 33764282, 2021). "Amebiasis is marked by acute inflammation with the release of cytokines (tumor necrosis factor alpha (TNFα), interleukin 8 (IL-8), IL-1β, interferon gamma (IFN-γ), reactive oxygen species (ROS), and nitric oxide (NO) from activated cells of the immune system." (PMID 30308066, 2018). "TNF-α is upregulated during amebic colitis in humans, and anti-TNF-α treatment protected mice from amebiasis." (PMID 28246365, 2017). "We concluded that IL-25 provides protection from amebiasis, which is dependent upon intestinal eosinophils and suppression of TNF-α." (PMID 28246365, 2017). "TNF-α was a critical cytokine mediator of tissue destruction during amebiasis and the anti-inflammatory cytokine IL-10 is an important immunoregulator." (PMID 26824828, 2016). "Our multi-omics analysis identified the shared molecules, regulators, and pathways at transcriptome and interactome layers in four diseases including TNF-alpha/NF-kappa B signaling, translation factors, amoebiasis, Interferon type I signaling, Cytokine signaling, and interleukin signaling." (PMID 38014119, 2023). "From these results, we hypothesized that suppression of TNF-α expression was a possible mechanism by which IL-25 mediates protection against amebiasis." (PMID 28246365, 2017). "Interestingly, expression of TNF and CXCL1 was higher in monocytes from male individuals than in those from females; this applied to both Ly6Chi monocytes in the murine model of amebiasis and CXCL1 in LPS-stimulated CD14++CD16- monocytes from healthy human subjects." (PMID 33829283, 2021).
bacterial meningitis (40 papers, 2007 to 2024). Inflammation of the membranes surrounding the brain and spinal cord due to a bacterial infection. "Direct inoculation of cerebrospinal fluid with Streptococcus pneumoniae in Mongolian gerbil model led to an increase in TNF-α circulation that was directly associated with bacterial meningitis and elevations in auditory brainstem response (ABR) thresholds." (PMID 32116980, 2019). "Additionally, it has been implicated in the generation of IL-6 and TNF-α pro-inflammatory cytokines through the stimulation of NFκB toward other forms of bacterial meningitis caused by N. meningitidis and B. bergdorferi." (PMID 35401413, 2022). "ZmpC was identified as a critical facilitator in the development of bacterial meningitis, as evidenced by the detection of increased expression of TNF-α, IL-8, and matrix metalloprotease 9 (MMP-9)." (PMID 39080654, 2024). "Once identified, cytokines such as tumor necrosis factor (TNF), interleukin-1 (IL-1A), among others, significantly increase in concentration within the cerebrospinal fluid during bacterial meningitis cases." (PMID 39877376, 2024). "The ELISA quantification results (pg/mg protein) showed that intranasal administration of bacterial meningitis in rats significantly stimulated the pro-inflammatory cytokines production, TNF-α, IL-6 and IL-1β, compared with the controls." (PMID 36015052, 2022). "Detailed Bayesian statistics was performed on three cytokines with key roles in inflammation in bacterial meningitis: IL-6, IL-8 and TNFα." (PMID 34620928, 2021). "In the pathogenesis of cerebral injury in bacterial meningitis, TNF-α, IL-6, and IL-1β are major early response cytokines that trigger, often in synergy, a cascade of inflammatory mediators, including other cytokines, oxygen intermediates, and chemokines." (PMID 34437417, 2021). "Several proinflammatory cytokines were found to be upregulated such as IL-1β and TNF-α, supporting increased inflammation as observed in bacterial meningitis cases." (PMID 32529267, 2020). "Elevated IL-8, IL-1β, TNF-α, and IL-6 have routinely been shown to be elevated in bacterial meningitis." (PMID 30626412, 2019). "They found that TNF-α, IL-1, IL-6, IL-8, IL-10, and IL-12 levels were significantly elevated in infants with bacterial meningitis." (PMID 30626412, 2019). "Multiple studies have demonstrated elevated levels of TNF-α, IL-6, and IL-8 in the CSF of patients with bacterial meningitis, especially in the pediatric population." (PMID 30626412, 2019). "Elevated CXCL5, CXCL8, and CXCL1 and TNFα CSF concentrations have been reported in children with bacterial meningitis." (PMID 31727097, 2019). "Cytokines such as TNF- α and IL-6 play an important role in bacterial meningitis to initiate and orchestrate the innate immune response in the early phase of the disease." (PMID 28915816, 2017). "Both rodents and patients with bacterial meningitis show an increased amount of TNF-α in the cerebrospinal fluid (CSF) in the early phase of the disease and TNF-α-deficient mice displayed an increased mortality after pneumococcal meningitis." (PMID 27057100, 2016). "Cytokines such as IL-6 and TNF-α play an important role in bacterial meningitis and are synthesized in large quantities by monocytes, macrophages, and leukocytes in response to bacterial stimuli." (PMID 27057100, 2016). "IL-6 was increased in aseptic and bacterial meningitis, whereas TNF-α was increased only in bacterial." (PMID 26286516, 2015). "We selected IL-1 beta, IL-6 and TNF alpha for the quantitative reverse transcriptase PCR, since they are known to be the major inflammatory cytokines detected in the CSF during bacterial meningitis, as control the house keeping genes GAPDH and HPRT1 were used." (PMID 23874613, 2013). "Increased mortality and spatial memory deficits in TNF-α-deficient mice with experimental pneumococcal meningitis were observed suggesting that TNF plays a role in inflammation and hippocampal injury in bacterial meningitis." (PMID 23997430, 2013).
bacterial meningitis (continued). "TNF of CSF increased significantly in bacterial meningitis, (P < 0.001)in viral meningitis, it increased various." (PMID 23483792, 2012). "Additionally, circulating TNF-α levels in CSF and plasma were higher in the bacterial meningitis group than in the control group." (PMID 39497833, 2024). "In addition, the levels of several inflammatory cytokines, such as interleukin (IL)-6, tumor necrosis factor (TNF)-α, IL-1β, and IL-18, are increased in the cerebrospinal fluid (CSF) of patients affected by bacterial meningitis." (PMID 35145923, 2021). "During a bacterial meningitis, TNFα and IL1 can be detected in CSF." (PMID 34863201, 2021). "In the present study, we detected reduced concentrations of TNF-α during bacterial meningitis in animals treated with HspB5 and observed attenuated hearing loss with better hair cell survival after recovery from infection in the these animals compared to the untreated cohort." (PMID 31244750, 2019). "Increased levels of IL-6 and TNF were detected in the CSF of patients with bacterial meningitis." (PMID 23483792, 2012). "The significantly higher CSF concentrations of IL-6, TNF-α, and MCP-1 are usually found in the acute phase of patients with bacterial meningitis, especially in patients with a fatal outcome." (PMID 37111486, 2023). "For the pathogenesis of bacterial meningitis, the cytokines and chemokines that are characteristically found in the CSF of patients, include IL6, IL8, TNFα, CXCL1 IL1β and MCP-1." (PMID 34863201, 2021). "A variety of cytokines have been demonstrated in the CSF of patients with bacterial meningitis, including interleukin-6 (IL6), interleukin-8 (IL8), interleukin-1-beta (IL1b), and tumor necrosis factor alpha (TNFa)." (PMID 34680826, 2021). "In bacterial meningitis, the majority (23/36) of examined cytokines displayed elevated values with CCL7, TNF-α, CXCL1, and IFNγ showing consistent results with the literature (; Pinto)." (PMID 31727097, 2019). "Regarding the TNF-α, previous reports suggest that TNF-α levels are increased only in bacterial meningitis." (PMID 26286516, 2015). "Cytokines and chemokines, including IL-8, IL-6, TNFα, MCP-1 and IL-1β, have been found in CSF during bacterial meningitis." (PMID 23448224, 2013). "Through this receptor, TNF-α can induce apoptosis of cells in already stressed cells; therefore, an adjuvant therapy against TNF-α could be relevant for treatment against bacterial meningitis, and indeed this has been shown to attenuate neuronal death in rats." (PMID 34149363, 2021). "On the other hand, it has been suggested that TNF-α might be responsible for BBB dysfunction and decrease of cerebral blood flow in bacterial meningitis as well as neuronal cell death." (PMID 27057100, 2016). "Additionally, pyroptosis causes the excessive production of cytokines and chemokines including TNF-α, IL-1β, IL-6, CCL3, CXCL-1, CXCL-2, etc. in bacterial meningitis which can also result in inflammatory mediator-induced neuronal damage." (PMID 26683708, 2015). "Still, we could not distinguish enteroviral meningitis from bacterial meningitis with the parameters of CSF cytokines IL‐2, IL‐6, IL‐10, TNF, and IFN‐γ." (PMID 31912935, 2020). "Thus, we could not distinguish enteroviral meningitis from bacterial meningitis with the parameters of CSF cytokines IL‐2, IL‐6, IL‐10, TNF, and IFN‐γ." (PMID 31912935, 2020).
hemorrhage (40 papers, 2009 to 2026). Loss of blood from the vascular compartment to the exterior or into nonvascular body space as a result of rupture or severance of the blood vessels. "PUGNAc and GlcN treatments also result in improved cardiac function and organ perfusion and reduced circulating levels of IL-6 and TNF-α in association with increased O-GlcNAc protein modification in the heart, liver, and kidney of rats subjected to trauma-hemorrhage." (PMID 21904602, 2011). "The -857T allele may produce a higher level of TNF-α, which may in turn decrease the hemorrhage size." (PMID 20534169, 2010). "The first heatmap analysis clearly demonstrates a significant reduction in larvae recovery, IFNγ, TNF, and hemorrhage in the reinfected (RE) groups compared to single-infected (SI) counterparts." (PMID 39621794, 2024). "In the ipsilateral region (around the hemorrhage), TNF-α was significantly increased on day 3, IL-1β on days 1 and 3, and IL-6 on day 1 after ICH compared to the sham group." (PMID 37190062, 2023). "Studies have found that nuclear factor‐κB (NF‐κB) in the tissues surrounding hematoma lesion will be activated 13–48 h after hemorrhage, and the expression levels of IL‐1β and TNF‐α increase within 1 day." (PMID 37614117, 2023). "Our study found that the intervention of ENA reduces the expression of TNF‐α, IL‐1β, and IL‐6 in the tissues around the hematoma lesion after hemorrhage, thereby reducing the inflammatory injury." (PMID 37614117, 2023). "In our study we confirmed this understanding and found that hemorrhages induced the expression of pro-inflammatory cytokines, TNF-α, and IL-1." (PMID 36297305, 2022). "Irisin-induced improvements to cardiac functions in this study were closely linked to the augmentation of cardiac functions, suggesting that attenuation in the production of TNF-α and IL-1 act as a mechanism for irisin’s cardiac effect in hemorrhage." (PMID 36297305, 2022). "A variety of inflammatory factors, such as TNF-α and IL-1β, are expressed around the hemorrhage area after cerebral hemorrhage." (PMID 35260880, 2022). "The Nlrp3 inflammasome, IL-1β, and TNF-α contributed to inflammation, coagulation defects, and hemorrhage." (PMID 33717109, 2021). "MetHb is an endogenous ligand of toll-like receptor 2 (TLR2) and toll-like receptor 4 (TLR4) that induces pro-inflammatory cytokine and tumor necrosis factor α (TNF-α) production after hemorrhage." (PMID 31357546, 2019). "The increase in serum levels of proinflammatory cytokines IL-1α, IL-1β, IL-6, and TNF-α in the groups submitted to hemorrhage agrees with findings in other studies showing greater production of these inflammatory mediators in renal injury." (PMID 29535870, 2018). "In several previous studies, 17-DMAG inhibits NO/iNOS pathway and TNF-α release via inhibiting NF-κB activation in hemorrhage-induced small intestine injury." (PMID 27224288, 2016). "Others have suggested that elevated plasma TNF-α and IL-6 induced by trauma-hemorrhage was prevented by estradiol treatment in rats." (PMID 24945834, 2014). "The serum TNF-α concentration in the Hemorrhage group was highest at 1 hour after hemorrhage and was significantly higher than in the Sham group at all timepoints (90.5±9.3 pg/ml at 1 hour, 62.0±9.1 pg/ml at 3 hours, 35.5±3.0 pg/ml at 5 hours)." (PMID 22253904, 2012). "Previous studies have shown that levels of IL-6 and TNF-α significantly increased following trauma-hemorrhage and remain elevated for several hours." (PMID 21649921, 2011). "Joint hemorrhage also increases TNF-α expression, which might strengthen the effect of mechanical stress." (PMID 33213419, 2020). "The relationship between TNF and hemorrhage is worth noting." (PMID 30409217, 2018). "Moreover, inhibition of TNF-α via an anti-TNF-α antibody decreases vasospasm and reduces expression of pro-apoptotic proteins in the single-hemorrhage model." (PMID 24386932, 2014).